MMP2 (matrix metallopeptidase 2)
Diseases named in the same sentence as MMP2 in open-access papers (continued):
Sharing a sentence is not in itself a finding about the gene and the disease.
aortic aneurysm (continued). "Matrix metalloproteinases-2 (MMP2), a gelatinase that has an important role in matrix degradation and vascular remodeling, is involved in many cardiovascular diseases, including aortic aneurysm formation, atherosclerosis, and myocardial fibrosis." (PMID 28164126, 2017). "Down-regulation of aortic PAR-2, Smad2/3 phosphorylation and MMP-2, and reduced monocyte/macrophage infiltration were demonstrated in a mouse model of aortic aneurysm following administration of the anticoagulant fondaparinux." (PMID 28220880, 2017). "Both in the animal models and human studies, aortic aneurysm correlated with an increase in aortic MMPs levels such as MMP-2, -3, -9 and -12." (PMID 27764090, 2016). "The fact, that pro-MMP-2 was present in all our control sera and in serum from healthy controls in other studies also illustrates, that serum MMP-2 has origins apart from aortic aneurysms." (PMID 27802285, 2016). "Previous studies reported activation of MMP-2 and MMP-9 being associated with formation of aortic aneurysms." (PMID 26539497, 2015). "This dilation is accompanied by histologic features of aortic aneurysms, including elastic fiber degeneration and an increase in apoptosis and a trend toward increased matrix metalloproteinase 2 (MMP2) expression in aortic smooth muscle cells." (PMID 25914885, 2015). "Initially we confirmed the up-regulation of Il6, Ccl4, Ccl8 and MMP2 within aortic aneurysms using real time PCR." (PMID 19580648, 2009). "Salvianolic acid modulates aortic aneurysm progression through the inhibition of MMP-2 and -9." (PMID 40565017, 2025). "Consequently, the expression of KLF5 and MMP2 is downregulated, leading to the suppression of cardiac hypertrophy and the attenuation of pathological changes in aortic aneurysms, respectively." (PMID 39252788, 2024). "Notably, MMPs are important in the development of coronary aneurysms and aortic aneurysms, and transgenic expression of MMP-2 induces coronary artery ectasia in mice models." (PMID 34912865, 2021). "TIMP2 inhibits the activity of MMP2, but it is also participatory in indirect activation of MMP2 through association with MMP14 that may promote cancer progression and, more importantly in the context of DSLD, aortic aneurysm development." (PMID 33028365, 2020). "Western blotting results revealed that NLRP3, MMP2 and MMP9, which induced the degradation of extracellular matrix (ECM), were dramatically increased in the human and mouse aortic aneurysm tissues compared with non‐aneurysmal tissues." (PMID 39601144, 2024). "MMP-2 and MMP-9 contribute to the pathogenesis of aortic aneurysm by cleaving the extracellular matrix of blood vessels." (PMID 37294581, 2023). "In agreement with this, several studies reported an increased expression and activity of MMP-1, MMP-2, MMP-3, MMP-9, and MMP-12 in aortic aneurysm tissues." (PMID 35456498, 2022). "On the other hand, TGF-β signaling pathway activation stimulates MMP-2 and MMP-9 production, which both determine matrix degradation, a key milestone in aortic aneurysm formation." (PMID 35563383, 2022). "In addition, since AA is a multifactorial disease, specific and few polymorphisms of TLR4 and MMP2 in the present study may not fully explain susceptibility to aortic aneurysmal diseases." (PMID 30530865, 2019). "Nevertheless, involvement of mediators of vascular remodeling, for example, metalloproteinases 2 and 9 (MMP-2 and MMP-9), as well as oxidative stress has also been shown in studies investigating aortic aneurysm specimen." (PMID 26539497, 2015). "Both MMP-2 and MMP-9 are also overexpressed in different Ang II infusion induced aortic aneurysm and aortic dissection models." (PMID 24194850, 2013). "Previous reports have demonstrated that MMP-2 and MMP-9, which are respectively derived from SMCs and macrophages, play important roles in the progression of aortic aneurysms." (PMID 22570740, 2012).
aortic aneurysm (continued). "Third, in mice, IH was demonstrated to increase vascular cell production of matrix metalloproteinases (MMPs) and metalloproteinases, including ADAM‐17 and the elastases MMP2 and MMP9, resulting in alteration of elastin in the aortic wall and the development of aortic aneurysms." (PMID 41541542, 2026). "In a mouse model of aortic aneurysm/dissection, the lesioned aortic tissue was accompanied by elastic lamina degradation, increased macrophage infiltration, and elevated expression of MMP9 and MMP2." (PMID 36830768, 2023). "In particular, single-cell transcriptomic profiling of VSMCs in Marfan syndrome aortic aneurysm revealed that MMP2 expression was significantly enriched in phenotypically modulated VSMCs, emphasizing a central role of MMP2 in ECM degradation and remodeling in aortic aneurysm." (PMID 35414069, 2022). "Recent studies have shown that the depletion of KIAA1462 decreased the expression of genes such as VCAM1, which is involved in the pathogenesis of ascending aortic aneurysm through increasing the activity of MMP-2 and MMP-9 that promotes aortic aneurysm progression." (PMID 35741789, 2022). "Moreover, experimental studies conducted on mice showed that both MMP-2 and MMP-9 act complementarily in aortic aneurysm development." (PMID 35563383, 2022). "Besides, gelatin zymography was used to measure activity of MMP-2 and MMP-9 in the wall of aortic aneurysms." (PMID 32382533, 2020). "Indeed, our results also showed UCP-2 knockout up-regulated the MMP2 and MMP9 expression in aortic aneurysm." (PMID 28683125, 2017). "MMP-2 and MMP-9 work in concert to produce aortic aneurysms." (PMID 29190959, 2017). "UCP-2 knockout up-regulated the MMP2 and MMP9 expression in aortic aneurysm." (PMID 28683125, 2017). "Even in the absence of MMP2 or MMP9, MT1-MMP can be a key regulatory factor to induce aortic aneurysm by promoting macrophage-dependent elastolytic activity in CaCl2-induced AAA109." (PMID 31857579, 2019).
breast tumor (53 papers, 2006 to 2026). "In a mouse model, the MPIs specifically inhibited MMP-2 and prevented breast tumor growth and its associated bone destruction." (PMID 33968752, 2021). "Overexpression of MMP-2 activity in MDA-MB-231 cells increased invasion in vitro, as well as distant metastases in nude mice, and high MMP-2 levels was associated with metastatic breast tumors." (PMID 16551362, 2006). "In addition, enhanced levels of MMP2 in breast tumors are associated with ErbB2 gene amplification and/or overexpression." (PMID 20649976, 2010). "Breast tumor cells excrete zinc-dependent proteases such as MMP-2 and MMP-9, which damage an integral part of the basal membrane, type IV collagen, resulting in cancer cells’ entry into the systemic circulation." (PMID 34535685, 2021). "Overexpression of MMP-2 and under-expression of TIMP-1 were associated with more invasive behavior in breast tumor cells." (PMID 31582999, 2019). "Our results are in agreement with the observation that MBP-1 expression results in the modulation of MMP-2 expression, the inhibition of in vitro angiogenesis and the regression of primary and metastatic breast tumor growth." (PMID 31416219, 2019). "Meanwhile, the MMP family are actively connected with biological changes, such as embryogenesis, and bone regeneration, from which MMP-9 and MMP-2 particularly works in the breast tumor." (PMID 29371992, 2017). "It is already known that fibronectin is capable of promoting the expression of MMP-2 in breast tumor cell lines." (PMID 25208219, 2014). "Both MMP-2 and -9 mRNA and protein levels have been shown to contribute to breast tumor invasion, metastasis and angiogenesis." (PMID 23536962, 2013). "In ER+ breast tumors E2 exerts a protective role since it regulates the expression both of MMP-2 and MMP-9 as well as syndecan-4 and, therefore, limits the ability of cells to invade the adjacent tissues." (PMID 23936773, 2013). "Recently, it has been shown that MBP-1 overexpression results in the modulation of MMP-2 expression, the inhibition of in vitro angiogenesis and the regression of primary and metastatic breast tumor growth in an immunocompetent mouse model." (PMID 20886042, 2010). "IL-17-dependent invasion of breast tumours was blocked by a range of selective MMP antagonists for MMP-2, MMP-3 and MMP-9 as well as a broad-spectrum MMP antagonist." (PMID 19014637, 2008). "Significant expression of N-Cadherin in tumor samples assayed in patients from G2, revealed the invasive state of the breast tumors similar to G1; and (iv) All the patients from G3 (doubtful cases) expressed detectable levels of Vim as well as meaningful levels of MMP2&9." (PMID 29259164, 2017). "Since several prometastatic genes (Plau, Mmp2, Mmp9, Has2, and Has3) were downregulated in Mbd2-KO PyMT tumors, we next used formalin-fixed lung tissue sections collected at the experimental endpoint and stained them with hematoxylin and eosin (H&E) to assess breast tumor metastasis to the lung." (PMID 38556549, 2024). "Thus, the differential expression of MMP-13 in breast tumor progression may be regulated by a mechanism different from those for MMP-2 and MMP-9." (PMID 18373849, 2008). "SOD2, iNOS, MMP2, MMP9 were evaluated through western blot and TUNEL test preformed for breast tumor." (PMID 39503169, 2024). "Boxplot representation of MMP2 and CHOP (E, G) expression in human breast tumors with low (IGF-1R z-score < − 1) versus high (IGF-1R z-score > 1) IGF-1R expression (Student’s t test, MMP2, P < 6.864 × 10− 10; CHOP, P < 3.172 × 10− 10)." (PMID 30458886, 2018). "TGFBI-expressing cells were found to inhibit tumor cell invasion through the downregulation of MMP-2 and MMP-9 in lung and breast tumor cells." (PMID 30453668, 2018). "In breast tumor D3H2LN cells, AngII upregulates MMP-2 / MMP-9 and ICAM1, which are involved in cell adhesion, migration, and invasion." (PMID 29179450, 2017).
breast tumor (continued). "As a whole, our data firmly establish Rab40b as a major regulator of targeted MMP2 and MMP9 secretion and breast tumor growth and metastasis in vivo and in vitro." (PMID 27789576, 2016). "Analysis of publicly available microarray data for human breast tumors showed a positive correlation between OPG and MMP-2 expression." (PMID 24976340, 2014). "Since the expression of MMP2 was shown to be increased by treatment with MDA-derived EVs, this would facilitate the digestion of ECM molecules such as collagen I, facilitating the invasion of breast tumor cells." (PMID 37569393, 2023). "Among MMPs, MMP-2 and MMP-9 are involved in breast tumor invasion." (PMID 36016682, 2022). "Although the invasive capacity of tumor cells appears to be unaffected by the presence of collagen fibril network in the invasion test, the expression levels of critical EMT markers, MMP-2 and MMP-9 have been shown to change when breast tumor cells are cultured in the presence of type I collagen." (PMID 30736469, 2019). "Overall, the partial screening of hydrolytic activity confirms the presence of thrombin (with or without PRP supplementation), trypsin-like serine proteinases, MMP-2 and MMP-9 metalloproteinases, and cathepsin-cysteine proteinases in the secretome of breast tumor cells." (PMID 28187434, 2017). "In vivo, metastatic human breast tumors had higher levels of MMP-2 than did non-metastatic tumor tissue, whereas adipocytes around metastatic breast tumors had higher levels of IGFBP-2 than did adipocytes surrounding non-metastatic breast tumors." (PMID 25747684, 2015). "By inhibiting MMP-2, an enzyme involved in tumor development, angiogenesis and metastasis, QSOX1 could disfavor breast tumor development and aggressiveness." (PMID 23098186, 2012). "Similarly, patients could also be taking anti-estrogens such as tamoxifen or fulvestrant, both of which have been shown to increase MMP2 and MMP9 secretion from breast tumor cells." (PMID 36765529, 2023). "In our study, we also confirmed that the mRNA expression levels of MMP2 was significantly upregulated in MTAP-knockdown BT20 cells but downregulated after ODC inhibitor DFMO treatment, indicating MTAP could block breast tumor angiogenesis via inhibiting the ODC-MMP2 signaling axis." (PMID 35541910, 2022). "Thus, MMP-13 may be independent of MMP-2 and MMP-9 as a marker as well as a regulator of breast tumor progression." (PMID 18373849, 2008).
Cerebral ischemia (53 papers, 2009 to 2025). Restriction of arterial blood supply to the brain associated with insufficient oxygenation to support the metabolic requirements of the tissue. "In cerebral ischemia models, MMP-2 cleaves PARP1 and XRCC1, two DNA repair enzymes, in vitro and in vivo to induce neuronal apoptosis." (PMID 39569367, 2024). "Our recent studies reported that free zinc accumulation in brain tissue leads to elevated MMP-2/-9 activation during cerebral ischemia." (PMID 37962463, 2023). "In this context, MMP-2/-9 dKO mice showed a delayed wound healing compared to WT mice and were protected from hemorrhagic transformation during early cerebral ischemia." (PMID 35804363, 2022). "A higher Ki of 14C-AIB and a higher level of MMP2 with Rapalink-1 in the IR-C indicate that BBB disruption was aggravated by Rapalink-1 in cerebral ischemia–reperfusion." (PMID 34354602, 2021). "Previous animal experiments have reported that cerebral ischemia results in the activation of MMP-2 and MMP-9 in brain tissue, leading to the degradation of occludin and destruction of the BBB." (PMID 32884584, 2020). "Morroniside protects against cerebral ischemia/reperfusion injury by inhibiting neuron apoptosis and MMP2/9 expression." (PMID 31827437, 2019). "MMP2 is also upregulated in the ischemic lesion, and however, only moderate levels of MMP2 induction were reported in experimental cerebral ischemia." (PMID 30723388, 2019). "The interactions between tPA and LRP1 or PDGFRα during cerebral ischemia increase the expression of MMP2 and MMP9." (PMID 30186167, 2018). "Previous studies have reported that MMP-9 activation is initiated as early as 4 h, which reaches the maximum level at 24 h and persists for at least 5 d after cerebral ischemia, whereas activated MMP-2 reaches the highest level 5 d after MCAo." (PMID 27703487, 2016). "The expression levels of MMP-9 and MMP-2 have been reported to start increasing from 12 h to 2 days and from 2 to 5 days after cerebral ischemia, respectively." (PMID 26637168, 2015). "Matrix metalloproteinase 2 (MMP2), aquaporin (AQP) 4, and AQP9 are linked to permeabilization of the blood-brain barrier (BBB) in cerebral ischemia/reperfusion injury (CIRI)." (PMID 24828425, 2014). "A study provided indirect evidence that MMP-2 played a key role in initial opening of the BBB after cerebral ischemia." (PMID 23565108, 2013). "After cerebral ischemia, levels of MMP-2 and MMP-9 are increased, which plays an active role in the formation of brain edema and the secondary brain injury." (PMID 23459987, 2013). "Overall, the neurological outcome in cerebral ischemia is improved by minocycline through MMP-2 and MMP-9 downregulation." (PMID 21110846, 2010). "The expression of the MMP-2 protein increased at 120 h of cerebral ischemia/reperfusion in rats, while the activation of MMP-9 expression increased significantly at 4 h of reperfusion, peaked at 24 h of reperfusion, and returned to normal at 120 h of reperfusion." (PMID 38927572, 2024). "MMP-2 mediated occludin degradation leads to BBB disruption during cerebral ischemia." (PMID 37962463, 2023). "In patients with acute MI, complicated with cerebral ischemia (CI) confirmed in cerebral computed tomography (CT), the levels of MMP-2 and MMP-9 as well as MMP-2 and MMP-9 mRNA expression were significantly higher in comparison with patients with MI, but without CI." (PMID 36835040, 2023). "Disruption of extracellular matrix by MMPs can induce anoikic in neurons and cerebral endothelial cells, indicating that MMP-2 may be an important target to prevent edema complications following cerebral ischemia." (PMID 36133785, 2022). "MMP-9, and MMP-2 played the most prominent role in cerebral ischemia." (PMID 29681849, 2018).
Cerebral ischemia (continued). "Single-dose of minocycline treatment immediately after reperfusion onset effectively reduces brain injury in rats subjected to transient focal cerebral ischemia due to inhibition on MMP-2/9-mediated occludin degradation and attenuation of caspase dependent and independent apoptotic pathways." (PMID 26925194, 2016). "However, during the acute phase of cerebral ischemia, the infiltrated leukocytes and reactive microglia synthesize and secrete MMPs (mainly MMP-2 and MMP-9) and ROS, thus increasing BBB permeability." (PMID 27703487, 2016). "The neuroprotective effects of the angiotensin receptor antagonists are well documented in experimental cerebral ischemia, but their robust vascular protective effects appear to be incompatible with the demonstrated ability to increase MMP-2 and MMP-9 activity." (PMID 25147751, 2014). "However, several CNS pathologies such as cerebral ischemia, multiple sclerosis and Devic's neuromyelitis optica are also associated with increased MMP-2 and-9 levels and MMP-9 inhibition is beneficial against cerebral ischemia." (PMID 21176168, 2010). "Furthermore, it has been shown that inhibition of MMP-2 and MMP-9 protects the blood-brain barrier during cerebral ischemia and that there is an increase in MMP-2 activity resulting from an increase in oxidative stress." (PMID 20205825, 2010). "The expressions of MMP-9 and MMP-2 are elevated after cerebral ischemia and able to open the BBB." (PMID 20514206, 2009). "MMP expression levels are very low under normal conditions, but the levels of MMP2 and MMP9 increase significantly within hours of cerebral ischemia." (PMID 41329542, 2025). "Both MMP-9 and MMP-2 played a key role in the disruption of the BBB with subsequent hemorrhage, brain infarction, and edema after cerebral ischemia." (PMID 39273389, 2024). "In our study, subacute administration of αPK reduced MMP-2 and MMP-9 levels and attenuated BBB breakdown and edema formation, supporting recovery after cerebral ischemia." (PMID 38872149, 2024). "As an important zinc-containing proteinase, MMP-2/-9 is crucial for degrading tight junction proteins, thus compromising BBB integrity during cerebral ischemia." (PMID 37962463, 2023). "In animal studies, the effectiveness of doxycycline and minocycline, derivatives of tetracycline, in inhibiting MMP-2 and MMP-9 in a rat model of cerebral ischemia was confirmed." (PMID 36835040, 2023). "In summary, our results show that during acute cerebral ischemia, inhibiting NADPH oxidase with apocynin reduced BBB damage by regulating HIF-1α upregulation and MMP-2 induction." (PMID 34434231, 2021). "OMS (0.01 or 0.1 μmol/kg per hour for seven days) reduced brain angiotensin II, MMP-2 and MMP-9 upregulation following brain ischemia." (PMID 32156050, 2020). "In the model of cerebral ischemia in mice, resveratrol was reported to significantly up-regulate the expression of VEGF and MMP-2, thereby attenuating ischemic brain damage in the delayed phase." (PMID 30564092, 2018). "These temporal profiles of expression after cerebral ischemia suggest a role of MMP-9 in secondary tissue damage and that of MMP-2 in tissue repair." (PMID 26637168, 2015). "Among them, MMP-2 and MMP-9 are major MMPs that are involved in BBB injury and neuronal death after cerebral ischemia." (PMID 25914628, 2015). "It seems that MMP-2 and MMP-9 expression is decreased after minocycline administration in rats with induced cerebral ischemia." (PMID 21110846, 2010). "MMP-2(gelatinase A) and MMP-9(gelatinase B) have been the focus of BBB studies in cerebral ischemia due to their ability to degrade the basement membrane due to their substrate specificity for the major components of the perivascular basement membrane, collagen IV, laminin, and fibronectin." (PMID 37483355, 2023).